ZRSR2P1 (ZRSR2 pseudogene 1)
Synonyms: U2AF1-RS1; U2AF1L1; U2AF1P; U2AF1RS1; U2AFBPL; ZRSR1; ZC3H21
Gene: Transcribed processed pseudogene on chromosome 5 (112,891,610 to 112,893,079, forward strand). Ensembl gene ENSG00000212643.
Subcellular location: Nucleus
Diseases named in the same sentence as ZRSR2P1 in open-access papers:
ZRSR2P1 is named in the same sentence as 8 diseases in open-access papers, as found by Europe PMC text mining. Sharing a sentence is not in itself a finding about the gene and the disease.
ZRSR2P1 shares sentences with these, for which no sentence is quoted: Azoospermia (1 paper); colorectal cancer (1); Hepatic steatosis (1); Infertility (1); Insulin resistance (1); mild cognitive impairment (1); Parkinson disease (1); steatosis (1).